H2AX (H2A.X variant histone)
Diseases named in the same sentence as H2AX in open-access papers (continued):
Sharing a sentence is not in itself a finding about the gene and the disease.
lymphoma (13 papers, 2011 to 2025). A malignant (clonal) proliferation of B- lymphocytes or T- lymphocytes which involves the lymph nodes, bone marrow and/or extranodal sites. "As many human lymphomas and solid tumors contain deletions of 11q23 on a single allele, loss of a single copy of H2AX gene might play a role in unleashing genetic instability in humans." (PMID 28914798, 2017). "To test this hypothesis, we examined the DNA damage level in G1XP lymphomas via detecting the phosphorylation of H2AX (at Ser 139), a variant of H2A." (PMID 26740101, 2016). "The association of H2AFX genetic variants with translocation-prone lymphoma subtypes supports the hypothesis that H2AX is required for optimal resolution of double-stranded breaks introduced during B-cell development." (PMID 24069324, 2013). "A prior report showed that BAY 1895344 increased the expression of p-H2AX, a marker of DNA DSBs, in lymphoma cell lines." (PMID 39941729, 2025). "Western analysis of PARP and phosphorylated H2AX expression levels in one representative cell line for each lymphoma subtype confirmed that addition of the ATM inhibitor to romidepsin increases the apoptotic effects of the HDACi." (PMID 32973968, 2020). "We used a flow cytometry-based method to measure γ-H2AX level in the G1XP lymphomas and in wt naïve (B220+PNAlow) and GC (B220+PNAhigh) B cells as controls." (PMID 26740101, 2016). "Doxorubicin-induced DNA damage was significantly increased in lymphoma cell lines exposed to a Pim kinase inhibitor, in association with significant downregulation of the DNA DSB response proteins H2AX, ATM and Chk2." (PMID 27374090, 2016). "Our data showed that G1XP lymphoma cells displayed a remarkably high level of γ-H2AX staining." (PMID 26740101, 2016). "Increased phosphorylation of γ-H2AX was observed in cells from two AML patients exposed to [Npb+DAC+Rom] and in cells from two lymphoma patients exposed to [Npb+DAC+Rom ± (Bu+Mel)], indicative of DDR activation." (PMID 29423093, 2018). "We observed that while wild type age matched littermate mice had very few gamma H2AX positive cells in their lungs (due to absence of lymphoma cells), the double mutant mice had a significantly high percentage of cells that stained positive for gamma-H2AX." (PMID 21799785, 2011). "In support of this concept, ATR/CHK1 pathway inhibition in combination with oncogene expression of H-rasG12V cells elevate H2AX phosphorylation to significantly higher levels than produced in control cells, and also ATR/CHK1 inhibitors are highly effective in killing Myc-driven lymphomas." (PMID 27167194, 2016). "Specifically, rs2509049 was associated with translocation-prone follicular (FL) and mantle cell (MCL) lymphomas, but not with diffuse large B cell lymphoma (DLBCL), consistent with a role for H2AX in prevention of translocations." (PMID 24069324, 2013).
triple-negative breast carcinoma (13 papers, 2011 to 2024). An invasive breast carcinoma which is negative for expression of estrogen receptor (ER), progesterone receptor (PR), and human epidermal growth factor receptor 2 (HER2). "Utilizing transcriptomics to determine whether H2AX loss affects metabolic genes in highly invasive triple-negative breast cancer cells, we found that H2AX-deficient cells exhibit repression of glycolysis genes." (PMID 35260660, 2022). "By suppressing the activities of Sirtuin 1 (SIRT1) and DNMTs, resveratrol and pterostilbene can synergistically inhibit cell viability, induce apoptosis, and arrest the cell cycle in triple-negative breast cancer cells, inhibiting telomerase activity and histone H2AX expression." (PMID 37111085, 2023). "However, gemcitabine has been shown to induce H2AX phosphorylation and Rad51 nuclear foci formation, i.e. markers of DNA double strand breaks, at stalled replication forks in triple-negative breast cancer cells." (PMID 21771338, 2011). "Under our experimental conditions, we also evaluated the genomic stability of triple-negative breast cancer MDA-MB-468 cells, which represents a key feature of the different cancer cells, by measuring the levels of phosphorylated H2AX histone (γH2AX)." (PMID 36140359, 2022). "Triple-negative breast cancers (TNBCs) exhibited the highest levels of phospho-Ser33-RPA32 (P < 0.001 for all tests) and γ-H2AX (P < 0.05 for all tests)." (PMID 32964114, 2020).
gastric cancer (12 papers, 2013 to 2025). A primary or metastatic malignant neoplasm involving the stomach. "The increased level of γ-H2AX was time-dependent indicating that NFATc3 knockdown did in fact cause DSB in gastric cancer cells." (PMID 31822296, 2019). "Chronic H. pylori infection, a risk factor for gastric cancer, also elicits an increased expansion of H2AX." (PMID 27045955, 2016). "It is also possible that, due to a single DSB being able to result in chromosomal translocations, deletions or loss of genetic information, several genes associated with tumor progression may be deleted in H2AX-positive gastric carcinoma tissues." (PMID 25789044, 2015). "In this study, the expression levels of γ-H2AX protein were assessed by immunoblotting in IGF2BP2-modified gastric cancer cell lines before and after exposure to radiation (4 Gy)." (PMID 40469197, 2025). "The western blotting results demonstrated that treatment of MKN45 and MGC803 cells with cisplatin for 24 h enhanced the expression of γ-H2AX levels, a DNA damage marker, indicating the induction of DNA damage in gastric cancer cells by cisplatin." (PMID 38871970, 2024). "It has been found that RNF43 depletion can impair the sensitivity to γ-radiation and chemotherapy by suppressing the activation of DNA damage response via directly targeting phosphorylated H2A histone family member X (γH2AX) in gastric cancer." (PMID 37848933, 2023). "Western blot analysis indicated that DNA-PKcs, ATR, Phospho-ATR, ATM, Phospho-ATM, γH2AX, and H2AX were upregulated in oxaliplatin-resistant gastric cancer cells, indicating that DNA damage repair response was activated in SGC-7901-R and KATO III-R cells." (PMID 33462197, 2021). "This indicates that NFATc3 was responsible for the increased level of γ-H2AX upon arsenic sulfide treatment of gastric cancer cells and demonstrates that arsenic sulfide induces DNA damage by inhibiting the NFATc3 pathway." (PMID 31822296, 2019). "The NOCs were observed to time-dependently induce DSBs and the expression of γ-H2AX in gastric cancer SGC7901 cells." (PMID 23833673, 2013). "Meanwhile, other studies affirmed that miR-138 can affect the proliferation, apoptosis, and invasion of lung, ovarian, and gastric cancer cells by targeting the expression of PD-L1, HIF-1α, SOX4, or H2AX." (PMID 35505294, 2022). "In addition, there was a negative correlation between DNA-PKcs and γ-H2AX levels in the precancerous lesions in pancreatic, intestinal and gastric cancer tissues." (PMID 33627782, 2021).
neuroblastoma (11 papers, 2013 to 2023). Neuroblastoma (NB) is the most common solid, extracranial childhood tumor. "In order to investigate H2AX phosphorylation, we performed Western blot analysis of whole cell lysates from proliferating and differentiated neuroblastoma SH-SY5Y cells and cybrids." (PMID 28842646, 2017). "To verify the role of BLM in neuroblastoma, we examined the expression of phosphorylated histone γ-H2AX, used as a marker for DNA double-stranded breaks, after infection of neuroblastoma cells with a BLM shRNA." (PMID 25477524, 2015). "Accordingly, we observed increased phosphorylation of DDR proteins and H2AX, enhancing the sensitivity to irradiation of PPM1D knockdown neuroblastoma cells." (PMID 34885154, 2021). "The obtained data testify that the THz exposure of 30 min does not change the number of the foci of histone H2AX phosphorylation either for neuroblastoma cells (SK-N-BE) or neural stem cells (drNPCs)." (PMID 37047534, 2023).
oral cancer (10 papers, 2012 to 2024). "Oridonin can induce apoptosis of oral cancer cells by phosphorylation of histone H2AX in response to DNA damage and inhibition of PI3K/Akt signaling." (PMID 37337284, 2023). "The percentage of g-H2AX-positive cells increased significantly following exposure of oral cancer cells to rapamycin." (PMID 36185289, 2022). "Flow cytometry analysis shows that WFA-treated Ca9-22 oral cancer cells induced G2/M cell cycle arrest, ROS production, mitochondrial membrane depolarization, and phosphorylated histone H2A.X (γH2AX)-based DNA damage." (PMID 28936177, 2017). "Here, we silenced FXR1 and estimated the level of γ-H2AX and pATM foci in both oral cancer cell lines." (PMID 27606879, 2016). "Moreover, ligustilide is able to increase the expression of γ-H2AX and enhance the occurrence of DNA damage in oral cancer cells after radiation treatment." (PMID 35494068, 2022). "Moreover, we have demonstrated that rapamycin dramatically induces DNA damage in oral cancer cells as measured by histone H2AX phosphorylation, one of the highly sensitive and general markers induced by chemotherapy." (PMID 36185289, 2022). "For further confirmation of the involvement of DNA damage in 4βHWE-induced inhibition of growth in Ca9-22 oral cancer cells, the DNA double strand break (DSB) was measured in terms of γ-H2AX expression." (PMID 23705007, 2013).
viral infection (10 papers, 2016 to 2025). "The virus productive infection also affects UV-primed DDR signaling, as demonstrated by the alteration of phosphorylated histone H2AX (γH2AX) protein levels and γH2AX formation following virus infection." (PMID 36140380, 2022). "So we predict that the upregulation of γ-H2AX, pChk1, and pChk2 in TIPE2 deficiency cells and HCC tumor tissue indicates that TIPE2 inhibits DDR during virus infection likely via the Rac pathway." (PMID 27696294, 2016). "This could have led to a stronger H2AX response than WT virus infection as a result of a higher abundance of input genomes when we used the same multiplicity of infection (MOI)." (PMID 33563816, 2021). "RNAseq and protein expression analysis ofDDB2,RAD17,PRKDC,PCNA and other ATR pathway markers of infected cells accompanied by time course studies of nascent double stranded chromosomal breaks (i.e. H2AX antibody staining due to viral infection) would provide such evidence." (PMID 33299552, 2020). "γ-H2AX was distributed in a diffuse nuclear pattern in several cells, distinct from the γ-H2AX foci typical of the response to PRVABC56 viral infection." (PMID 29022904, 2017). "H2AX phosphorylation represents a cell type-specific and virus type-specific host response to HSV infection with little impact on viral infection." (PMID 26817608, 2016). "Collectively, these observations suggest that H2AX phosphorylation represents a cell-specific and virus-specific host response to HSV infection and that such phosphorylation has little impact on viral infection." (PMID 26817608, 2016). "In non-targeting PK15 cells, PRV and VSV infection increased γ-H2AX levels to 1.6 and 2.4 times, respectively, suggesting that viral infection induces more DNA damage, in agreement with the previous publications." (PMID 39861880, 2025). "The detection of γH2AX in some, but not all TAg-expressing cells in PyVAN biopsies suggests that H2AX is not phosphorylated in all phases of virus infection." (PMID 34372559, 2021).
lung adenocarcinoma (9 papers, 2017 to 2025). A carcinoma that arises from the lung and is characterized by the presence of malignant glandular epithelial cells. "Meanwhile, lung adenocarcinoma cells in the NPs + RT group showed an increase in the percentage of γ-H2AX positive cells." (PMID 34372869, 2021). "Similarly, we found that AM-101 enhances γ-H2AX in lung adenocarcinoma cells." (PMID 39335139, 2024). "We first exposed the lung adenocarcinoma NCI-H838RBM14/NCI-H838luc and NCI-H1650RBM14/NCI-H1650luc cell line pairs to 2 Gy ionizing radiation (IR), and by immunofluorescence measured levels of nuclear γ-H2AX foci as a biomarker of DNA damage." (PMID 39870664, 2025). "Our findings in lung adenocarcinoma cell line and xenografts support that USP22 could promote the phosphorylation of histone H2AX via deubiquitinating histone H2A, thus contributing to the DNA damage repair induced by cisplatin and leading to cisplatin resistance." (PMID 28567015, 2017).
ataxia telangiectasia (8 papers, 2010 to 2025). Ataxia-telangiectasia is the association of severe combined immunodeficiency (affecting mainly the humoral immune response) with progressive cerebellar ataxia. "The increase in γ-H2AX phosphorylated at Ser139 by protein kinase ATM (mutated in ataxia-telangiectasia) leads to the recruitment of the mediator of DNA damage checkpoint protein 1 (MDC1) as a response to the formation of double strand breaks (DSB)." (PMID 32357578, 2020). "γ-H2AX is predominantly mediated by an ataxia telangiectasia mutation (ATM) through continued phosphorylation proximal to DNA breakage sites which spreads to adjacent areas of chromatin." (PMID 20565729, 2010). "In the AT5BIVA fibroblast cell line derived from a classical ataxia telangiectasia patient, there is again a predictable induction of DNA DSB indicated by the appearance of γ-H2AX foci." (PMID 22170789, 2012). "Cells established from NBS patients survive following irradiation, but retain γ-H2AX foci due to a subtle DSBs repair defect, albeit at a lower level compared to Ataxia telangiectasia (AT) lymphocytes (characterized by the absence of the ATM protein)." (PMID 25485873, 2014). "Additionally, we aspire to integrate lymphocyte proliferation assays into routine practice and develop new functional tests, such as the assessing of histone H2AX phosphorylation (γH2AX) in CD3 T cells following irradiation, commonly used in diagnosing Ataxia Telangiectasia and radiosensitive SCIDs." (PMID 39072316, 2024).
liver cancer (8 papers, 2020 to 2024). An epithelial or non-epithelial malignant neoplasm that arises from the liver. "Similarly, in renal cell and liver cancers, high expression of H2AX is an unfavourable prognostic marker (source: proteinatlas.org); advanced stage (I versus II–IV), H2AX high expressing breast tumours also showed significantly worse OS (p = 0.007) and DFS (p = 0.001)." (PMID 32887437, 2020). "Herein, differently to what described in liver cancer cells, HDAC3 depletion alone is ineffective in inducing phosphorylation of H2AX (i.e., γH2AX), a marker of DNA damage, but highly enhances IR-induced γH2AX increase." (PMID 39107280, 2024). "We first examined spontaneous γ-H2AX and 53BP1 foci formation in 10 primary tumor cell lines derived from CRISPR/Cas9-induced mouse liver cancer, the control cell line NIH3T3, and the mouse liver cancer cell line Hepa1-6." (PMID 37803452, 2023).
non-small cell lung carcinoma (8 papers, 2014 to 2025). A group of at least three distinct histological types of lung cancer, including non-small cell squamous cell carcinoma, adenocarcinoma, and large cell carcinoma. "Treatment of non-small cell lung cancer cells with 6 mM ascorbate increased the expression of γ-H2AX, p-Chk1, and p-RPA2, and disrupted the accumulation of DNA repair factors at damaged sites via H2O2 production." (PMID 39990670, 2025). "This is the first study using γ-H2AX, a DNA damage biomarker, as input in a prognosis prediction model of patients with early operable non-small cell lung cancer." (PMID 24527431, 2014). "The aim of the present study was to predict the outcome of patients with early operable non-small cell lung cancer using ANNs by incorporating γ-H2AX, a new DNA damage response biomarker." (PMID 24527431, 2014). "For the first time, γ-H2AX, a DNA damage biomarker, was used in a prognosis prediction model of patients with early operable non-small cell lung cancer." (PMID 24527431, 2014). "Our research team was the first to demonstrate that overexpression of γ-H2AX may represent an independent prognostic indicator of worse overall survival in patients with non-small cell lung cancer." (PMID 24527431, 2014). "This study indicates that neural networks may represent a potentially more useful decision support tool than conventional statistical methods for predicting the outcome of patients with non-small cell lung cancer and that some molecular markers, such as γ-H2AX, enhance their predictive ability." (PMID 24527431, 2014). "The CG oleandrin has been shown to induce DNA damage in non-small cell lung cancer (NSCLC) A549 adenocarcinoma cells as measured by surrogate markers including RPA and γ-H2AX foci." (PMID 37584722, 2023). "Co-immunoprecipitation and WB studies with lysates from MDA-MB-468, UOK262, and non-small-cell lung cancer (HCC827 and H1975) cells revealed CARP-1 interaction with H2AX." (PMID 30769864, 2019).
sarcoma (8 papers, 2011 to 2025). A usually aggressive malignant neoplasm of the soft tissue or bone. "H2A variants like H2AX, H2AZ, and H2A1 were previously reported to be altered and implicated in several cancer types, including sarcoma, breast, colorectal, brain tumor, and head and neck." (PMID 40565234, 2025). "Measuring across Pot1b−/− sarcoma generations, γ-H2AX TIF formation was undetectable in G1 to G3 Pot1b−/− nuclei but ∼10% of G4 Pot1b−/− nuclei exhibited γ-H2AX TIFs with increasing TIF rates measured with each subsequent generation." (PMID 37560909, 2023). "We used cell proliferation and apoptosis assays in sarcoma cell lines and benign cells; γ-H2AX expression, comet assay, immunoblot analyses and drug combination studies in vitro and in patient derived xenograft (PDX) models." (PMID 27248664, 2016). "Furthermore, γ-H2AX TIFs were also detected in ∼9% of nuclei from a second independent late-generation Pot1b−/−; Pot1a+/+ sarcoma cell line." (PMID 37560909, 2023). "Therefore, our data suggest that high levels of phosphorylated H2AX might be an independent marker of poorer prognosis in sarcoma patients." (PMID 32963243, 2020). "In this study, we explored the role of H2AX phosphorylation at Ser139 alone or in combination with MAP17 protein, an inducer of DNA damage through ROS increase, as prognostic biomarkers in sarcoma tumors." (PMID 32963243, 2020). "Indeed, evaluation of phospho-H2AX (Ser139)(hereafter γH2AX), a surrogate marker of DSBs, indicated that SN-38 treatment induced higher levels of DSBs in EwS in comparison to non-EwS sarcoma cells." (PMID 40721661, 2025).